INS (insulin)
Diseases named in the same sentence as INS in open-access papers (continued):
Sharing a sentence is not in itself a finding about the gene and the disease.
Hypoglycemia (continued). "Insulin-based treatment regimens may also be complex, and this, together with a fear of adverse effects, such as hypoglycaemia, may adversely impact adherence to treatment." (PMID 29408938, 2018). "The beneficial effects of 3-HB shown in this study suggest that hypoketonemic severe hypoglycemia induced by insulin injections or insulin secretagogue administration may be more harmful than hyperketonemic severe hypoglycemia." (PMID 29554103, 2018). "Theoretically, in some of the diabetic trauma patients hypoglycaemia may have been a consequence of anti-hyperglycaemic drug overdose from insulin or anti-diabetic drugs." (PMID 30005711, 2018). "Furthermore, in this study, the majority of T2D patients reporting hypoglycemia unawareness were on insulin treatment." (PMID 29593644, 2018). "While any improvement in A1c is likely better care for the patient,this may be obtained with a more focused approach of obtaining a low FBG goal now with the use of basal insulin and may reduce theincidence of hypoglycemia." (PMID 31404422, 2018). "Modular architecture allows AP systems to be assembled from independent (but compatible) modules, each performing a specific function, e.g. prevention of hypoglycemia, post-meal insulin corrections, fine tuning of basal rate, or administration of ancillary compounds such as amylin or glucagon." (PMID 32232090, 2018). "It has been suggested that for complete prevention of exercise-induced hypoglycemia, bihormonal systems, involving both insulin and its antagonist, glucagon, may be more successful, as they would better replicate the hormonal changes that usually take place." (PMID 30081478, 2018). "In addition, hypoglycemia is usually a side effect of treatment with blood-sugar-lowering medication, such as insulin therapies in both types of the disease." (PMID 32232085, 2018). "The principal factors associated with insulin nonadherence were fear of hypoglycemia, interference with daily activities, a greater number of applications per day, and economic factors." (PMID 30116737, 2018). "IAS may occur with fasting or exacerbated exercise hypoglycemia; however, it is classically characterized by late postprandial hypoglycemia, high insulin levels, and positive results for anti-insulin antibodies." (PMID 30462811, 2018). "His parents note that he has repeated hypoglycemia with marked reduction of insulin requirements." (PMID 29682577, 2018). "However, since we found no relevant effect on diurnal glucose control, and rather, an aggravation of fasting hypoglycemia during the night, we decided to test continuous subcutaneous mecasermin infusion using an insulin pump." (PMID 29695048, 2018). "Endogenous insulin production by islet transplantation combined with optimal insulin therapy was shown to be sufficient to maintain near-normal glucose levels and avoid hypoglycemia." (PMID 30030637, 2018). "The purpose of this study was to develop and validate a prediction model for insulin-associated hypoglycemia in non-critically ill hospitalized adults." (PMID 29527311, 2018). "The most recently marketed Degludec, which is a long-acting insulin analog with a prolonged half-life and ultra-flat kinetics, is the best choice in DM1 patients requiring lower HbA1c targets with the consequent potential higher risk of hypoglycemia." (PMID 30918874, 2018). "In sensor-augmented pump therapy, for example, the insulin pump may suspend insulin delivery if the predicted glucose concentration crosses a preset hypoglycemia threshold." (PMID 30067409, 2018). "First, the sample size for this study is too small to reveal the association between QTc intervals and serum potassium levels and the changes in serum norepinephrine level which have been reported in studies investigating norepinephrine kinetics in response to insulin-induced hypoglycemia." (PMID 30105256, 2018). "However, we did use the gold standard stimulation test (insulin-mediated hypoglycemia) for both GH and cortisol." (PMID 29681937, 2018).
Hypoglycemia (continued). "The results presented suggest that introducing basal insulin analogues in these persons can significantly improve glycemic control and reduce the risk of hypoglycemia, with no deleterious impact on body weight." (PMID 29460260, 2018). "In a separate study, IDegLira provided glycaemic control superior to that of insulin degludec at equivalent insulin doses, without a higher risk of hypoglycaemia and with the benefit of weight loss." (PMID 29408938, 2018). "Examination of the functional state of β cells with c-Myc revealed numerous observations—β cells secreted high insulin in low glucose leading to hypoglycemia, exhibited poor GSIS, and had compromised expression of important function-maintaining genes, closely resembling an immature functional state." (PMID 29396395, 2018). "Furthermore, avoid/reduce the dose of insulin in people with CKD who have a tendency to develop hypoglycemia." (PMID 29527102, 2018). "Studies that evaluated the utility of basal morning serum cortisol measurements in the diagnosis of adrenal insufficiency showed that a threshold of 10 mcg/dL leads to 77% of specificity, and 62% sensitivity, defined by a subnormal serum cortisol response to insulin-induced hypoglycemia." (PMID 29867608, 2018). "The risk for delayed postprandial hypoglycemia is not reduced relative to other rapid-acting insulin products, nor does Fiasp address adherence issues associated with subcutaneous insulin administration." (PMID 29707584, 2018). "In conclusion, insulin-associated hypoglycemia in non-critically ill hospitalized adults can be predicted on the basis of EMR data." (PMID 29527311, 2018). "The Hypoglycemia Assessment Tool study in Brazil aimed to determine the proportion of patients experiencing hypoglycemic events and to characterize patient awareness and fear about hypoglycemia, among insulin-treated T1DM or T2DM patients." (PMID 30479669, 2018). "One exception was a randomised trial in individuals with IAH wherein an insulin analogue-based regimen produced a 29% reduction in the number of episodes of severe hypoglycaemia per person-year when compared with a regimen of soluble (regular) and NPH (intermediate-acting) insulin." (PMID 29423581, 2018). "Although our study was not performed in PWDs, our results are applicable, since the physiological response to fasting-induced hypoglycemia is identical to that of insulin-induced hypoglycemia, and exposure to fasting-induced hypoglycemia produces HAAF-like symptoms in humans." (PMID 29931424, 2018). "In diabetic dialysis patients, hypoglycemic agents and nutritional alterations can trigger hypoglycemia in the background of diminished gluconeogenesis, reduced insulin clearance by the kidney, and improved insulin sensitivity following initiation of renal replacement therapy." (PMID 30538746, 2018). "Early initiation of insulin in older patients was found to be beneficial without increasing risk of hypoglycemia or greater total direct healthcare costs." (PMID 29527102, 2018). "Interestingly, the insulin‐dose resulting in hypoglycemia was increased from 40 nmol/kg insulin alone to 160 nmol/kg insulin in the 1:23 ratio." (PMID 29595915, 2018). "However, while Trls2+/+ and Trls2+/- mice displayed similar insulin levels, Trls2-/- mice showed significantly decreased insulin, which was expected given the hypoglycemia." (PMID 29466436, 2018). "There has been significant research into insulin-related hypoglycaemia." (PMID 30417151, 2018). "We should becautious in initiating continuous intravenous insulin in these cases,because insulin requirements may decrease rapidly in the immediatepostoperative period, resulting in severe hypoglycemia." (PMID 30652752, 2018). "Traditionally, an insulin bolus has been administered to overcome the insulin resistance seen during a hyperglycemic crisis, but in more recent years this practice has come into question, given the concern for hypokalemia and hypoglycemia." (PMID 30544554, 2018).
Hypoglycemia (continued). "The only considerable side effect related to insulin therapy is hypoglycemia." (PMID 29682315, 2018). "Possible adverse effects of insulin therapy include hypoglycemia which may promote adrenergic discharge, fluid retention and electrolyte imbalance, increasing the risk for life-threatening arrhythmias." (PMID 29402330, 2018). "However, modern insulin analogues report lower incidence of hypoglycemia than traditional human insulins." (PMID 29527102, 2018). "Of note, in malaria patients, hypoglycemia only develops in an insulin-dependent manner upon quinine treatment (quinine induces insulin), whereas in patients not treated with quinine, life-threatening hypoglycemia also develops in an insulin-independent way, similar to our observations in mice." (PMID 30375380, 2018). "Restoration of hepatic glycogen content could represent a mechanism for combatting hypoglycemia, as hepatic glycogen is the predominant source of blood glucose during exercise and insulin overcorrection." (PMID 30116746, 2018). "If persistent hypoglycemia is encountered, insulin infusion should be stopped." (PMID 30148167, 2018). "The improved daily glucose variability observed with IDegAsp might be attributable to the stable glucose-lowering effect of the insulin degludec component, which generally leads to strict titration with less fear of nocturnal hypoglycemia." (PMID 30127860, 2018). "Due to potential severe hypoglycemia, euglycemia using insulin-providing strategy in T2DM patients may be difficult." (PMID 29545773, 2018). "In addition, the frequency of hypoglycemia increased in our patients using a sulfonylurea or insulin, but those patients recovered once the dose of that medication was adjusted." (PMID 29695055, 2018). "During the insulin-induced hypoglycemia test, a cortisol concentration of 30 μg/dL was observed." (PMID 30542321, 2018). "Our analysis indicates that the paradoxical stimulation of insulin secretion by glucagon minimizes overshoots in blood glucose levels following reversion of hypoglycemia, but has a notable vulnerability - glucose levels drops are accentuated (low minimum after drops)." (PMID 30013127, 2018). "A meta-analysis of studies in which patients with T2D received a GLP-1RA with basal insulin has shown the combination provides good glycaemic control without increasing the risk of hypoglycaemia or weight gain." (PMID 29408938, 2018). "Thus, despite hypoglycemia in Lis1 KO mice, these animals were more tolerant to glucose and insulin than the controls." (PMID 29475944, 2018). "In addition to glucagon, the counter regulatory responses to insulin-induced hypoglycemia include the increase of various hormones, such as glucocorticoids and catecholamines." (PMID 29880854, 2018). "Hypoglycemia is a common complication following the use of glucose and insulin for hyperkalemia." (PMID 28245289, 2017). "The noted hypoglycemia may be due to the improvement of β-cell ultrastructure, thus directing improved insulin levels, which aids glucose uptake with normoglycemia." (PMID 28448463, 2017). "In addition, results from our study indicated that, compared to participants with NGT, participants with biochemical hypoglycemia had higher levels of insulin sensitivity, as evaluated by Matsuda ISI." (PMID 28913363, 2017). "We hypothesise that the significant reductions in glucose variability and hypoglycaemia by closed-loop insulin delivery in our study might have implications for clinical outcomes, although this hypothesis will need confirmation by longer and larger studies." (PMID 28094136, 2017). "It improved HbA1c, FPG, and body weight at a relatively decrease in insulin dose without remarkably risk of hypoglycemia." (PMID 28538386, 2017). "Thus, linagliptin treatment significantly ameliorated hypoglycemia in klotho−/− mice, probably independently of insulin." (PMID 29195509, 2017).
Hypoglycemia (continued). "Second, titrating appropriated doses of insulin is not an easy task, and patients are susceptible to hypoglycemia." (PMID 29138181, 2017). "However, hypoglycemia becomes progressively more frequent, depending upon the history of hypoglycemia and the duration of insulin treatment." (PMID 28115020, 2017). "Indeed, the simultaneous infusion of glucose and GLP-1 in healthy volunteers, mimicking the glycaemic and insulin peaks in patients with dumping syndrome, does provoke hypoglycemia." (PMID 28185153, 2017). "The relatively mild hypoglycemia, induced by low dose of insulin, may have rendered the inhibitory pathways of GE inoperative, apparently without activating stimulatory pathway." (PMID 28876363, 2017). "However, the importance of hypoglycemia in intensive insulin therapy compared to conventional therapy should be paid more attention." (PMID 28271075, 2017). "However, its use is recommended as add-on to insulin, in which case cautious glucose monitoring is necessary to prevent severe hypoglycemia." (PMID 29270438, 2017). "Although this study shows that hypoglycaemia was not present during exercise, the risk would be greater following habitual T2D medication, particularly sulfonylureas and insulin." (PMID 28634587, 2017). "This helps in the early recognition of possible side effects such as hypoglycemia from some antiglycemic medications like sulphonylurea and insulin and the spatial trend of glucose profiles that may need dose adjustments." (PMID 29270319, 2017). "This may be accounted for as follows: the use of long-acting insulin degludec led to decreases in fasting glucose levels but was also responsible for nocturnal hypoglycemia unawareness." (PMID 28683068, 2017). "With regards to insulin initiation, most of the concerns are similar to those reported elsewhere including insulin signifying an increased degree of illness severity and adverse effects mainly hypoglycemia." (PMID 28405339, 2017). "Hypoglycemia is a serious complication following the administration of insulin for hyperkalemia." (PMID 28245289, 2017). "The study demonstrates that the fasting blood glucose of patients with insulinoma is lower than that of patients with hypoglycemia, and the fasting insulin, the fasting C-peptide, and the fasting IRI of patients with insulinoma are higher than those of patients with hypoglycemia." (PMID 28293303, 2017). "A continued supply of glucose to the patient during the duration of action of the administered insulin might contribute to reduce the incidence of hypoglycemia even further." (PMID 28245289, 2017). "Subcutaneous insulin poses a risk of hypoglycaemia during subsequent exercise, and data in this study are not sufficient to mitigate this concern." (PMID 28634587, 2017). "Therefore, the blunted counter-regulatory response observed in the STZ+EX group cannot be attributed to antecedent hypoglycemia or repetitive insulin treatment." (PMID 28570686, 2017). "Therefore, to avoid hypoglycemia, the preexercise short-acting insulin dose must be reduced for safety reasons." (PMID 28662684, 2017). "Three were regarded potentially preventable due to misunderstanding of a dose increase of metoprolol (usual care), insufficient self-management of a hypoglycemia due to insulin masked by metoprolol use and hyponatraemia due to hydrochlorothiazide for a second time (COACH program)." (PMID 28445474, 2017). "Initial insulin dose was associated with a higher risk of severe hypoglycemia in those with BMI <30, whereas no covariates were identified with higher risk in the ≥30 group." (PMID 28151905, 2017). "These additional recommendations are stated in the PS but come from other studies: for low- to moderate-intensity aerobic activities lasting 30–60 min during fasting or basal insulin conditions, ~10–15 g of carbohydrate may suffice to prevent hypoglycemia." (PMID 28265261, 2017).
Hypoglycemia (continued). "Refractoriness of nNOS and GAD65/67 proteins to hypoglycemia alone supports the view that glycogen mobilization over an initial 2 h period after insulin injection may be sufficiently robust to have negligible impact on GABA‐ or nitrergic signaling." (PMID 29199177, 2017). "SGLT2 inhibitors have improved the HbA1c, FPG, and body weight when combined with insulin and decreased the dose of insulin without increasing the risk of hypoglycemia." (PMID 28538386, 2017). "Several studies have investigated the effect of acute insulin-induced hypoglycaemia in rats with blood glucose levels of 2-3 mmol/l or even below 2 mmol/l, that is, levels that may induce isoelectric EEG and coma." (PMID 28421113, 2017). "Rapid decline in plasma glucose and inappropriate insulin secretion following glucose load suggested that mutations in UCP2 cause glucose-induced HH rather than fasting hypoglycaemia." (PMID 28855921, 2017). "This insensitivity leads to a lower first-phase insulin secretion to the rising postprandial glucose but a subsequent exaggerated compensatory second-phase insulin secretion, which might result in hypoglycemia." (PMID 28913363, 2017). "Indeed, Chga-KO mice show improved hepatic insulin sensitivity as assessed by insulin tolerance tests (ITTs) showing increased hypoglycemia, and insulin clamp studies showing increased suppression of HGP." (PMID 28228748, 2017). "However, the incidence of neonatal hypoglycemia was higher in the glyburide group compared to the insulin group." (PMID 28771572, 2017). "However, due to the failure of insulin dose titration and fear of hypoglycemia, insulin treatment is perceived as a complex and reluctant therapy by both patients and doctors." (PMID 28720103, 2017). "The majority of trials (88%) included outcomes in the ‘metabolism and nutrition’ domain, such as lipids and lipoproteins (21%), HbA1c (18%), hypoglycaemia (14%), fasting plasma/blood glucose (11%), glycaemic variability (8%), postprandial response (8%) and insulin sensitivity (5%)." (PMID 29246177, 2017). "NPH (neutral protamine Hagedorn) insulin carries low risk of hypoglycemia in individuals without any significant past history, and is low cost." (PMID 28167928, 2017). "Timing may be another critical issue, since a smaller dose of glucose or the administration of the insulin bolus before the infusion of glucose have been related to hypoglycemia events." (PMID 28245289, 2017). "Combined with the potential of insulin treatment to preserve muscle function and mass, it should be emphasized that insulin treatment should be initiated with the careful consideration of adverse effects, particularly hypoglycemia." (PMID 28246927, 2017). "Although GH response to insulin-induced hypoglycemia was low, she had a normal height of 161 cm." (PMID 28588004, 2017). "Meanwhile, nocturnal hypoglycemia was 25% less frequent among those on insulin degludec." (PMID 28683068, 2017). "However, no studies thus far have investigated the relationship between glycemic variability and nocturnal asymptomatic hypoglycemia in patients receiving insulin degludec by using CGM." (PMID 28683068, 2017). "Besides, insulin had the highest incidence of NICU admission, acarbose had the lowest risk of neonatal hypoglycemia." (PMID 28930827, 2017). "Insulin- and sustained running-induced hypoglycemia increases GE of liquid in rats." (PMID 28876363, 2017). "Hypoglycemia is a common adverse effect of insulin treatment for T2DM21." (PMID 28067320, 2017). "The grade 4 hypoglycemia resolved completely after adjusting insulin treatment." (PMID 28938918, 2017). "It has been recently suggested that activation of peripheral β2-adrenoceptors (possibly in the liver) and of the ventromedial region of the hypothalamus also occurs in rats with insulin-induced hypoglycemia as a counter-regulatory response for the recovery of glycemic levels." (PMID 28876363, 2017).